RNU6-875P (RNA, U6 small nuclear 875, pseudogene)
Gene: Small nuclear RNA gene on chromosome 8 (123,342,414 to 123,342,519, forward strand). Ensembl gene ENSG00000252297.
Homologues: Orthologues: chimpanzee U6 (98% identical), rat LOC120100203 (49% identical), macaque U6 (48% identical). Paralogues in human: RNU6-1122P (75% identical), RNU6-1029P (74% identical), RNU6-238P (74% identical), RNU6-1131P (73% identical), RNU6-1243P (73% identical), RNU6-1266P (73% identical), RNU6-24P (73% identical), RNU6-43P (73% identical), RNU6-476P (73% identical), RNU6-727P (73% identical), RNU6-1011P (72% identical), RNU6-1020P (72% identical), and 1285 more.